STX19 (syntaxin 19)
Description:
Plays a role in endosomal trafficking of the epidermal growth factor receptor (EGFR).
Synonyms: MGC21382
Tractability: Antibody: UniProt places it where antibodies can reach, with medium confidence; its Gene Ontology location is reachable by antibodies, with medium confidence. PROTAC: ubiquitination databases record sites on it.
Gene: Protein-coding gene on chromosome 3 (94,012,043 to 94,028,654, reverse strand). Ensembl gene ENSG00000178750.
Subcellular location: Cell membrane; Cytoplasm
Subcellular location (Human Protein Atlas): Intermediate filaments; Cytosol
Gene Ontology:
Molecular function: protein binding; SNARE binding; SNAP receptor activity
Biological process: exocytosis; synaptic vesicle fusion to presynaptic active zone membrane; intracellular protein transport; vesicle-mediated transport
Cellular component: cytoplasm; plasma membrane; presynaptic active zone membrane; membrane
Genetic constraint (gnomAD): Loss-of-function variants: 26 observed, 25.42 expected, observed/expected ratio (o/e) 1.02, 90% interval 0.75 to 1.42. The upper end of that interval is the gene's LOEUF score, 1.42, which puts it in group 5 of 6, group 1 being the genes least tolerant of losing a copy. Missense variants: 367 observed, 346.87 expected, observed/expected ratio (o/e) 1.06, 90% interval 0.97 to 1.15. Synonymous variants: 116 observed, 112.18 expected, observed/expected ratio (o/e) 1.03, 90% interval 0.89 to 1.21.
Homologues: Orthologues: chimpanzee STX19 (99% identical), macaque STX19 (98% identical), rabbit STX19 (91% identical), dog STX19 (91% identical), pig STX19 (90% identical), mouse Stx19 (86% identical), rat Stx19 (84% identical), guinea pig STX19 (84% identical), tropical clawed frog stx19 (62% identical), Caenorhabditis elegans syx-3 (21% identical), Caenorhabditis elegans syx-2 (18% identical), Caenorhabditis elegans syx-4 (18% identical). Paralogues in human: STX11 (36% identical), STX1A (29% identical), STX1B (29% identical), STX3 (29% identical), STX2 (27% identical), STX4 (26% identical), STX5 (17% identical), STX12 (17% identical), STX17 (17% identical), STX16 (16% identical), STX7 (15% identical), TSNARE1 (13% identical).
Diseases named in the same sentence as STX19 in open-access papers:
STX19 is named in the same sentence as 6 diseases in open-access papers, as found by Europe PMC text mining. Sharing a sentence is not in itself a finding about the gene and the disease. The quoted sentences say what the papers report.
breast carcinoma (1 paper, 2025). "Other downregulated genes of interest, Gsdmc, linked to other cancers, and Stx19, a gene with little prior breast cancer research, also warrant further investigation." (PMID 40925719, 2025).
mammary adenocarcinoma (1 paper, 2017). "Syntaxin 19 (or epimorphin, as it is also termed) was at least in the murine system associated with the promotion of alveolar hyperplasia and mammary adenocarcinoma." (PMID 28402269, 2017).
viral infection (1 paper, 2021). "The most down-modulated genes were related to T helper 2 pathway activation and induction of FOXP3 expression (AREG), immune tolerance (SMAD6), response to bacterial and viral infection and inflammation (CXCL8, PDE12, STX19, DFNB31), cell transport of glucose and organelles (KIF5A, SCL2A7)." (PMID 35058920, 2021).
tumor (1 paper, 2017). "The second most down-regulated gene was neuritin 1 (NRN1), which has been proposed as hypoxic marker and potential marker for tumor angiogenesis, followed by the proline-rich nuclear receptor coactivator 2 (PNRC2), syntaxin 19, and early growth response 1 (EGR1)." (PMID 28402269, 2017).
STX19 also shares sentences with these, for which no sentence is quoted: autism (1 paper); cancer (1).